GNAS (GNAS complex locus)
Diseases named in the same sentence as GNAS in open-access papers (continued):
Sharing a sentence is not in itself a finding about the gene and the disease.
tumor (continued). "Approximately one-third of the PA-ACS group harbour mutations of cortisol producing lines like PRKACA and GNAS with higher cortisol levels and tumour diameter than PA-ACS subjects without these mutations." (PMID 36428832, 2022). "We did not observe significant relationship between GNAS mutation and demographical/clinical features including patients’ age, gender, pathological diagnosis, invasiveness status, and tumor size." (PMID 36497102, 2022). "Beyond tumor initiation, contradicting roles of the GNAS signaling have been reported on tumor growth and maintenance, which may be influenced by the timing of different mutational events." (PMID 34201897, 2021). "Although GNAS mutation is proved to be an important promoter in mucin secretion of PMP, the current experiment was performed in colorectal cancer cell lines due to the difficulties in the culture of PMP tumor cells." (PMID 32700107, 2020). "One potential target in low-grade tumours is the G-protein-coupled receptor GNAS." (PMID 32733093, 2020). "Additionally, immunochemical analysis showed that p-STAT3 expression was evidently decreased in the tumor tissues of the GNAS-cas9 group, compared to that in the WT group." (PMID 32123532, 2020). "The GNAS c.601C>T variant was present in three tumor samples while none of the gDNA samples contained this variant." (PMID 31620080, 2019). "Therefore, the potential downregulation of GNAS by miR-145-5p would be consistent with the here proposed tumor suppressive role of miR-145-5p." (PMID 30886199, 2019). "Thus, widespread inactivating mutations in Gi/o-linked GPCRs similarly suggests that their restraining activity on GNAS is lost and, as part of the tumorigenic process, cAMP signalling is persistently activated and leads to tumor progression." (PMID 31337866, 2019). "Five of the genes affected by a single technology indel (WGS) in the MSI tumor (GNAS, HOXC13, MAPK1, and ZFHX3) and two of the genes affected by a single technology indel (WGS) in the MSS tumor (GNAS and HOXD13) were also listed in the cancer gene census list of the COSMIC database." (PMID 28683819, 2017). "Nine GNAS mutant tumors (90%) harbored concomitant activating mutations in either the KRAS or BRAF oncogene, which was significantly greater than the mutation frequency of these genes in the tumor population (56%, p<0.0305)." (PMID 24498230, 2014). "Although variants with similar functional consequences have occasionally been described in LCTs of adult patients, including a tumour with a hotspot codon 201 GNAS mutation, most tumours in this age group do not harbour alterations associated with MAPK pathway activation." (PMID 41384702, 2026). "This study also unveils novel insights into the mutational landscape of LSTs, revealing frequent mutations in codon 186 (p.R186C/R186H) of the GNAS gene, unique to LSTs and absent in colorectal adenomas, associated with specific tumor locations (rectum) and pathological types (villous adenomas)." (PMID 40943367, 2025). "The differences in GNAS and KRAS mutational status and unique pathological behavior observed in the intestinal subtype support the potential driver role of GNAS in histopathological tumor development with unique outcomes that may promote GNAS status as an early prognostic marker itself." (PMID 40002298, 2025).
tumor (continued). "Six patients underwent molecular testing on tumor DNA: two carried marked IC2-LoM, two exhibited loss of heterozygosity (LOH) at chromosome 11p15, one carried somatic pathogenic variants of CTNNB1 and GNAS genes, and one carried somatic pathogenic variants of the MKRN3 and CYP17A1 genes." (PMID 39682154, 2024). "It has been suggested that a minimum of 10% tumor cell fraction is required to detect GNAS pathogenic variants, but the tumor cell fraction may have not been estimated accurately." (PMID 38317844, 2024). "Tumor localization, radiology, and absence of GNAS mutation reinforced the diagnosis of BFH." (PMID 38374215, 2024). "Of note, tumor exhibited a heterogeneous phenotype with a tumor component displaying glial differentiation, with robust GFAP expression, and a component with conventional MB features and selective presence of GNAS mutation, suggesting co-existence of two different major tumor subclones." (PMID 36941703, 2023). "Moreover, the finding that GNAS copy number gain can markedly enhance tumor cell proliferation implied that an inhibitor therapy targeting CDK6 may be effective for PIT1 lineage patients harboring GNAS copy number gain." (PMID 36307579, 2022). "Overall, our results suggested that the GNAS relaxation and loss of A/B DMR methylation could be one of the steps in the dedifferentiation drift including a loss of GNAS, AIP and SSTR2 expression that may contribute to the tumor promotion." (PMID 34299200, 2021). "GNAS mutations seem to be related more to mucin production rather than tumor proliferation." (PMID 33266161, 2020). "The GNAS R201H mutation in the tumor tissue of patient 23 could not be found in bile even after manual inspection of sequencing reads." (PMID 33375555, 2020). "None of the analyzed tumor tissue samples contained GNAS c.680A>T somatic variant." (PMID 31620080, 2019). "These analyses revealed no KRAS/BRAF/GNAS/PIK3CA mutations in all tumor samples." (PMID 30116990, 2018). "Identification of novel tumor-wide neoantigens from RNA splicing erros, such as GNAS and RPL22, enhances T cell therapy by recognizing and eradicating cancer cells across various tumor types." (PMID 40563429, 2025). "For the spatial visualization of RNA and gene expression, we found that the prognostic genes from XGBoost model, especially GNAS, ATP1A1, ATP1B1, colocalized with the densest regions of tumor." (PMID 39678375, 2024). "In GNAS-mutant pancreatic tumor cells, PKA-mediated suppression of the salt-inducible kinases (SIK1-3) supports tumor growth." (PMID 36692000, 2023). "We observed amplifications in chromosome arm 20q (chr20q) in 74/373 tumours (19.8%), which includes SRC, TOP1, BCL2L1, ZNF217, AURKA, GNAS and ARFRP1." (PMID 37666855, 2023). "Genetic analysis reveals that MC1R signals through the GNAS-PKA axis to repress the transcription of chemokine genes CXCL9/10/11, resulting in impaired T cell infiltration into the tumor microenvironment." (PMID 37714844, 2023). "By activating the GNAS-PKA axis, MC1R inhibits interferon-gamma induced CXCL9/10/11 transcription, thus impairing T cell infiltration into the tumor microenvironment." (PMID 37714844, 2023). "However, the GNAS R844H mutation was captured in all cfDNA samples during the clinical course of the patient, including the pretreatment, suggesting this mutation was, in fact, not captured in the tumor biopsies because of tumor heterogeneity." (PMID 35263170, 2022).
tumor (continued). "Detection of tumor type-specific alterations, including AR, ESR1, GNAS, and EGFR alterations in seven samples, as well as EBV, HBV, and MSI positivity in three samples, informed potential tumor origins." (PMID 35486650, 2022). "Overview of correlation of tumour grade, IDH1, IDH2 and GNAS mutant profile pre‐ and postoperatively." (PMID 34528398, 2021). "The study on incidence of tumor and development of carcinoma found that some DEPs indirectly inhibited the occurrence and development of MF, including CLU, GNAS, FZR1, and PKM." (PMID 33299887, 2020). "Overall, these results indicate that GNAS is frequently upregulated in HCC tissues and promotes tumor masses." (PMID 32123532, 2020). "Indeed, the chromosome alterations affecting the H19, KCNQ1OT1, PLAGL1 and GNAS DMRs also affected one or more WT driver genes in all analyzed cases, and the chromosome variants affecting the MEST, GRB10 and MEG3 DMRs also affected tumor driver genes in at least 83% of cases." (PMID 33217932, 2020). "Other possible signatures of recurrent tumour resistance in this GBM cohort included CNV gains in the genes (chromosome), BRCA2 (Chr13), GNAS (Guanine nucleotide-binding protein G(s) subunit alpha; Chr20), and EGFR (Chr7)." (PMID 32082376, 2019). "Moreover, we investigated the KRAS/BRAF/GNAS/PIK3CA mutational status (mutational analysis for exon 2 of KRAS, exon 15 of BRAF, exons 9 and 20 of PIK3CA, and exons 8 and 9 of GNAS) of the original tumor (pancreatic head) and the recently resected tumors from the pancreatic body and tail." (PMID 30116990, 2018). "The dynamic changes observed in key mutations such as BRAF, APC, GNAS, EGFR, and PIK3CA suggest that ctDNA analysis can offer unique insights into tumor evolution that are not captured by traditional tissue biopsies." (PMID 39796090, 2024). "The GNAS gene, involved in cAMP‐PKA pathways, was found to contribute to tumor cell proliferation." (PMID 37787018, 2023). "Among them, ERBB4 and NPM1 are presumably involved in cSCC tumorigenesis; in addition, GNAQ, GNAS, JAK2, NRAS, IDH2, and CTNNB1 may be related to tumor metastasis." (PMID 36780540, 2023). "In contrast, expression of the GNAS R201C mutant did not lead to faster tumor growth in comparison to expression of wild-type GNAS in NCG mice." (PMID 37714844, 2023). "In contrast, when transplanting tumor cells expressing the wild-type or the R201C mutant forms of GNAS into the NCG mice, we did not observe significant difference in tumor growth or host survival time." (PMID 37714844, 2023). "Furthermore, the GNAS copy number gain group had higher multigene proliferation score (MGPS) and clinical tumor volume as compared with the WT group (Wilcoxon test, P < 0.05)." (PMID 36307579, 2022). "A copy gain on chromosome 20q was observed for three, including one gsp-positive tumor, but GNAS expression was not significantly increased in comparison to tumors without copy gain." (PMID 34299200, 2021). "Interestingly, eight among the overlapped hypermethylated genes (WT1, PAX6, GNAS, EPB41L1, CSMD1, CPEB1, RERG, and SMAD6) were previously reported to exhibit tumor suppressive functions." (PMID 34462486, 2021). "The 20–30% of central cartilaginous tumours without an IDH1/2 mutation highlights the need for additional prognostic biomarkers for patients whose tumours are WT for IDH1, IDH2 and GNAS mutations." (PMID 34528398, 2021).
tumor (continued). "In particular, germline and somatic genome alterations (AIP, MEN1, GNAS, and USP8), dysregulated signaling pathways (Notch, Wnt, TGF-β, and cell cycle regulation), and tumor microenvironment factors were characterized, while the role of other species of RNA awaits full characterization." (PMID 33808624, 2021). "Investigated molecules without connection to common key tumor proteins are GNAS, USP8, USP48, HHIPL1, NNAT, RHOU, C5orf66 and RASSF3, which seem to be more specific biomarkers and therefore should be validated for concordant differences in liquid biopsies." (PMID 32498309, 2020). "In summary, these results demonstrated that CLU, GNAS, and PKM are differentially expressed in the serum of MF patients and normal subjects, which may inhibit the occurrence and development of tumor directly/indirectly." (PMID 33299887, 2020). "It speculated that the upregulated expression of CLU, GNAS, and PKM may inhibit the occurrence of tumor in the early stage, while the expression decreased in the late-stage promotes the development of tumor." (PMID 33299887, 2020). "Among the tumor-related genes, the top amplified genes included ERBB2 (17q21), MYC (8q24), GNAS (20q13), EGFR (7p11), ZNF217 (20q13), CCNE1(19q12), NCOA3 (20q13), and CDK6 (7q21), and the most frequently deleted genes were CDKN2A (9p21), CDKN2B (9p21), KIT (4q12), SMAD4 (18q21), and FGFR1 (8p12)." (PMID 31541076, 2019). "Tumor genetic defects in USP8, GNAS, USP48 and BRAF are some of the commonly encountered tissue-specific changes and may explain a larger percentage of the developed tumors." (PMID 31877737, 2019). "Moreover, several genes (such as BCAR3, GNAS, ISLR and RASGRP3) exhibited opposite patterns of AS events of a parent gene in tumor and normal tissues." (PMID 31695792, 2019). "In conclusion, mutations in GNAS and abnormal PTTG and AIP expression had no impact on tumor features and treatment outcomes in this cohort." (PMID 29947650, 2018). "Taken together, the simultaneous activation of GNAS- and KRAS–dependent pathways might cooperatively promote tumor genesis in various gastrointestinal organs." (PMID 24312577, 2013). "A previous study of mucinous appendiceal neoplasms found wild‐type GNAS in 5/6 high‐grade tumours, raising the possibility that high‐grade lesions may not arise from low‐grade tumours." (PMID 39435876, 2024). "Additionally, GNAQ, GNAS, JAK2, NRAS, IDH2, and CTNNB1 are cancer-related genes that may be related to tumor metastasis." (PMID 36780540, 2023). "In addition to mutations, epigenetics or other regulatory mechanisms reducing RNF43 expression could play an analogous effect synergizing with GNAS in the formation of IPMN and other neoplasia in the pancreas." (PMID 29544460, 2018). "Given the activated IFN signature observed in the combined GNAS KO plus RGFP966 condition and the critical role of IFN signaling in anti-tumor immune responses, we explored whether GNAS KO can synergize with HDAC3 inhibition to promote anti-tumor immunity such as CD8+ T cell-induced cytotoxicity." (PMID 39117798, 2024). "Although the roles/functions of the GNAS mutations in IPMN or PDAC have not been elucidated, these mutations may be associated more with tumour initiation than with tumour progression because the mutation has also been observed in low-grade tumours." (PMID 24897499, 2014).
tumor (continued). "Consistently, we demonstrated that the addition of cAMP analog 8-Br-cAMP led to a varied degree of anti-tumor effects in all three DLBCL cell lines and GNAS KO did not alter cAMP levels which appeared to be already low in the control cells." (PMID 39117798, 2024). "Genome-wide CN analysis of the 13 intrinsic-resistant tumours revealed NRG1 and GNAS amplifications in CRC tumours without any aberrations in RAS/RAF pathway genes." (PMID 31653970, 2019). "Although no specific tumour-related gene was shared among the three groups, NOTCH2 was shared between BTG and PTCb while AR, HSP90AB1 and GNAS were shared between BTG and PTCa suggesting their possible roles in the BTG-to-PTCb and BTG-to-PTCa transformation, respectively." (PMID 36686473, 2022).